IL6 (interleukin 6)
Diseases named in the same sentence as IL6 in open-access papers (continued):
Sharing a sentence is not in itself a finding about the gene and the disease.
Stroke (continued). "Similarly, the study showed that IL-6, produced locally by resident brain cells promotes angiogenesis in the delayed phases of stroke recovery." (PMID 36678774, 2022). "Interestingly, we found a positive correlation between the concentration of IL-6 and TNF-α in patients with AIS assessed in <4.5 h and 1 day after the stroke, which means that the concentration of IL-6 rises with the increase in TNF-α concentration." (PMID 36142524, 2022). "When a stroke occurs, IL-6 in the brain is mainly derived from activated astrocytes and microglia." (PMID 35419117, 2022). "IL-6 may be vital to stroke recovery and stem cell functionality, as exemplified by the following studies." (PMID 36555094, 2022). "In stroke patients, serum IL-6 levels are significantly increased and positively correlated with cortisol levels, suggesting that IL-6 release after cerebral ischemia may contribute to hyperactivation of the HPA." (PMID 36211352, 2022). "SCFAs have been associated with elevated levels of systemic proinflammatory markers IL-6, TNF-α, vascular cell adhesion molecule-1(VCAM-1), IL-17, and MCP-1 after stroke, which was associated with a high disease burden at discharge and the duration of inpatient recovery." (PMID 36389714, 2022). "Indeed, in the present study, higher levels of IL-6 were independently associated with a higher CNFD and CNFL, despite a loss of corneal nerves in patients with TIA and stroke." (PMID 35228650, 2022). "In addition, the levels of IL-6 in serum are correlated with cerebral infarction volume and stroke severity." (PMID 35173738, 2022). "The complexity in controlling IL-6 signaling to improve stroke recovery may be due to precise temporal and environmental-based changes influencing IL-6′s preferred signaling." (PMID 36555094, 2022). "In conclusion, we show greater corneal nerve loss in patients with stroke and TIA compared to healthy controls and contrary to our initial hypothesis we show that elevated IL-6 levels were independently associated with greater corneal nerve measures." (PMID 35228650, 2022). "Additionally, TLR4 is also responsible for chronic neuroinflammation leading to brain damage after stroke, as it induces the production and release of TNF-α, IL-6, and NO, causing neuronal cell death." (PMID 35283778, 2022). "This study suggests that the enhanced production of exosomal miR-134 in stroke patients might induce intercellular brain injury via IL-6 and other cytokines." (PMID 36438184, 2022). "To evaluate the effects of serpinA3N on pro‐inflammatory responses after stroke, we measured the expression of inflammatory cytokines interleukin (IL)‐6 and tumor necrosis factor (TNF)‐α and found that IL‐6 and TNF‐α were significantly lower in serpinA3N‐overexpressed mice at 24 h poststroke." (PMID 34897996, 2022). "Patients with elevated levels of both IL-6 and YKL-40 also had increased risk of recurrent stroke (adjusted HR, 1.37; 95% CI 1.14–1.63; P = 0.0007), poor functional outcome (adjusted OR 1.36; 95% CI 1.17–1.58; P < 0.0001) and dependence or death (adjusted OR 1.91; 95% CI 1.56–2.34; P < 0.0001)." (PMID 35761288, 2022). "Moreover, it has been reported in stroke that the release of interleukine-6 (IL-6), a marker of inflammation, is enhanced by tPA through activation of NMDARs and upregulation of endothelin-1 (ET-1) and c-Jun N-terminal kinase (JNK)." (PMID 36142247, 2022). "Generally, cytokines such as TNF-α and IL-6 are upregulated in the brain after a stroke." (PMID 36076942, 2022). "Nonetheless, a careful examination of IL-6, specifically detailing its timing and dosing regimen post-stroke, may reveal the optimal strategy to exert therapeutic effects." (PMID 36555094, 2022).
Stroke (continued). "dBET1 markedly reduced inflammation and oxidative stress after stroke, indicated by multiple pro-inflammatory cytokines and chemokines including IL-1β, IL-6, TNF-α, CCL2, CXCL1 and CXCL10, and oxidative damage markers 4-hydroxynonenal (4-HNE) and gp91phox and antioxidative proteins SOD2 and GPx1." (PMID 35761277, 2022). "IL-6: a pro-inflammatory cytokine with unclear function in stroke." (PMID 35795571, 2022). "If timely intervention and effective regulation of IL-6 expression in the body can be achieved, it can not only reduce the adverse prognosis of stroke but could also reduce the damage of heart function." (PMID 35419117, 2022). "When compared to blood samples, CSF IL-6 levels have been found to be significantly higher in patients with multiple sclerosis, subarachnoid hemorrhage, ventriculostomy-related infection, bacterial meningitis, traumatic brain injury, and stroke." (PMID 35898322, 2022). "The effect of IL-6 on brain endothelial cells in the context of stroke and ischemia-reperfusion injury remains clear; however, the question of whether brain endothelial cells are a major source of IL-6 in this context remains unclear." (PMID 36145501, 2022). "IL-6 released into the cerebrospinal fluid after stroke may lead to impaired cerebrovascular autoregulation and increased histopathology." (PMID 35173738, 2022). "First, TNF‐α, IL‐6, IL‐1β, and IL‐18 are known to be key influential modulators of diabetes, as also cytokines which are upregulated during the systemic immune response to stroke." (PMID 35971650, 2022). "The authors noticed a strong correlation between high levels of interleukin-6 (IL-6) and soluble interleukin-2 receptor (sIL-2R) and embolic stroke of undetermined source (ESUS) suggesting that the cause for embolic strokes was hypercoagulability associated with inflammation." (PMID 36289812, 2022). "However, IL-6 is upregulated in microglia and cortical neurons in stroke rats, and increases of IL-6 are more pronounced in the case of gray matter lesions." (PMID 34122007, 2021). "Since IL-6 is an inflammatory mediator closely associated with PSD, we speculated that elevated RDW-CV and RDW-SD might be observed in patients with stroke who are at high risk for the occurrence of PSD." (PMID 34335867, 2021). "Elevated blood levels of inflammatory cytokines such as C-reactive protein (CRP), Interleukin-6 (IL-6), IL-18, IL-12, tumor necrosis factor-α, and C–C chemokine ligand 2 (CCL-2) were associated with poor outcome and increased mortality after stroke." (PMID 34336007, 2021). "Moreover, circulating IL-6 predicted the severity of depressive symptoms assessed at 3 months after stroke." (PMID 33903586, 2021). "Numerous inflammatory mediators in the peripheral circulation, such as C-reactive protein (CRP) and interleukin-6 (IL-6), are altered in the acute phase of stroke and could have a role as biomarkers of prognosis or impending complications." (PMID 34753981, 2021). "Therefore, previous myocardial infarction, stroke, chronic kidney disease and liver disease should be evaluated for their effects on miRNA-222, IL-6 and NT-proBNP." (PMID 33593281, 2021). "Regarding long-term mortality, it has been revealed that IL-6 could also predict mortality both 1 year and 2 years after stroke." (PMID 33578805, 2021). "In addition, in our mixed effect model, we also found that the combination of atorvastatin and aspirin decreased IL-6 secretion from co-cultures of stroke Mo and MSCs." (PMID 33959001, 2021). "Circulating biomarkers which constitute the typical lipid patient profile (LDL-C, TC, triglyceride, Ox-LDL, Lp-PLA2), inflammatory biomarkers such as hs-CRP, TNF-α, IL-6, adipokines (adiponectin, leptin, FABP4) and homocysteine are related to the high risk of future stroke." (PMID 34829489, 2021). "Moreover, the serum levels of TNF-α and IL-6 were markedly increased in the subacute phase of stroke, which were reversed by QSYQ (600 mg/kg)." (PMID 33953667, 2021).
Stroke (continued). "Interestingly, our results show that stroke per se leads to systemic inflammation characterized by a significant increase in plasma levels of IL-6 in MCAO groups independently of the diet conditions as compared to SHAM groups." (PMID 33925459, 2021). "Intriguingly, both IMAT and pro-inflammatory adipokines, TNFα and IL-6, were found to be locally increased in the paretic leg of stroke survivors, suggesting that the inflammatory milieu could be locally conditioned by IMAT quantity." (PMID 34025446, 2021). "Salivary TNF-α, IL-6, and IL-10 may be potential non-invasive biomarkers that distinguish stroke patients from controls with high sensitivity and specificity." (PMID 34433866, 2021). "In the current study, it is found that compared to patients with non-PolyVD and IL-6 <2.64 pg/ml, patients with elevated IL-6 levels had the higher risk of recurrent stroke and MACEs, especially patients also with PolyVD." (PMID 33927687, 2021). "IL-6 is also widely known for its role in immunopathology of several diseases including stroke." (PMID 33668216, 2021). "Also, it has been proved that the level of IL-6 was increased in patients with stroke and was correlated with stroke severity." (PMID 34504432, 2021). "As an upstream and potent inflammatory factor, IL-6 was closely related to adverse stroke outcomes." (PMID 33927687, 2021). "In this study, it is also observed that the risk of recurrent stroke and MACEs increased significantly in patients with PolyVD, compared to those with non-PolyVD and IL-6 <2.64 pg/ml." (PMID 33927687, 2021). "IL-6 has several potentially essential functions in the pathogenesis of stroke." (PMID 34504432, 2021). "Altogether, endostatin, TNF-R1, and IL-6 circulating levels may aid in long-term mortality prediction after stroke." (PMID 33578805, 2021). "The inflammatory cytokines, tumor necrosis factor-alpha (TNF-α) and interleukin-6 (IL-6), are generally considered to be representative contributors to neuroinflammation in ischemic stroke and are therefore promising potential targets in future stroke therapy." (PMID 33953667, 2021). "Interestingly, using multiple logistic regression, plasma IL-6 was shown to be an independent factor for early clinical deterioration in stroke patients." (PMID 34433866, 2021). "In addition, stroke per se produced an acute systemic pro-inflammatory state reflected by diet-independent increase in plasma IL-6 levels." (PMID 33925459, 2021). "Our aim was to study a serum glutamate/IL-6 ratio as an index for stroke onset definition." (PMID 34300300, 2021). "Additionally, peak plasma levels of IL-6 in the first week of ischemic stroke significantly related to infarct volume at 5-7 days post-stroke, as well as clinical outcome at 3 months." (PMID 33971895, 2021). "Elevated IL-6 predicts adverse outcomes in patients after acute coronary syndrome; however, the influence of elevated IL-6 on recurrent IS after stroke could be less profound." (PMID 34575712, 2021). "Plasma IL-6 predicted the severity of depressive symptoms assessed at 3 months after stroke." (PMID 33903586, 2021). "Administration of an IL-6 neutralizing antibody to both singly- and pair-housed mice prior to ischemia onset resulted in infarct sizes that were comparable between groups, thereby mitigating the influence of housing conditions on stroke outcome." (PMID 32477259, 2020). "In the Health, Aging, and Body Composition study of 2225 participants 70 to 79 years old without baseline cardiovascular disease, IL-6 was significantly associated with all outcomes, including coronary heart disease, stroke, and congestive heart failure." (PMID 32438719, 2020). "Activated microglia are characterized as proinflammatory or anti-inflammatory microglia; microglia activation occurs within hours after stroke, and several pro-inflammatory factors (such as Il-1, Tnf-α, and Il-6) can be released by microglia in response to synapse degeneration or loss." (PMID 32473633, 2020).
Stroke (continued). "The results showed that I/R induced obvious cerebral infarction and neurobehavioral defects, in parallel with histological aberrations and extensive signaling of proinflammatory cytokines, including tumor necrosis factor (TNF-α) and interleukin-6 (IL-6), in the stroke model." (PMID 32714088, 2020). "The level of IL-6 at the early stage of stroke is negatively correlated with the prognosis of neurological function and might be considered as a key biomarker to predict the prognosis." (PMID 33328961, 2020). "Furthermore, male stroke rats display significantly reduced expression of inflammatory IL‐6 and caspase‐3, suggesting that combined therapy for BM‐MSCs with PGZ counters neuroinflammation." (PMID 32356605, 2020). "Furthermore, mice treated with A151 showed a dampened immune response to stroke, with reduced counts of neutrophils, microglia, and microglial production of IL‐6 and TNF‐α after MCAO." (PMID 32239625, 2020). "Within minutes after injury, injured neurons and glial cells in the core and penumbra of the stroke produce pro-inflammatory mediators, including interleukin-6 (IL-6), interleukin-1 β (IL-1β), and tumor necrosis factor-α (TNF-α), which activate both astrocytes and microglia." (PMID 32595496, 2020). "The level of IL-6 in the serum is positively correlated with the exacerbation of stroke." (PMID 33076354, 2020). "Interestingly, increases in the systemic inflammatory response measured by circulating TNF-α and IL-6 were observed along with changes in fecal microbiome at the acute stage of stroke." (PMID 33343283, 2020). "On its side, IL-6 plasma levels also correlate with stroke severity and poor clinical outcome." (PMID 33362697, 2020). "Furthermore, it allowed us to grasp the effect of systemic inflammation because the blood IL-6 level rises between 6 and 72 h after the onset of stroke symptoms." (PMID 32107751, 2020). "As shown on an animal model of brain damage, IL‐6 and IL‐10 release results from sympathetic activation as well as catecholamine release due to increased intracranial pressure following the occurrence of stroke." (PMID 32583980, 2020). "Interestingly, IL-6 mRNA levels were significantly elevated in the gut even at 7 days after stroke in aged mice compared to the age-matched sham controls." (PMID 32429999, 2020). "Similarly, we found increased systemic pro-inflammatory cytokines IL-6 and G-CSF levels in aged mice at both 6 h and at 24 h after stroke." (PMID 32429999, 2020). "Plasma levels of the pro-inflammatory cytokine interleukin-6 (IL-6) on days 5–7 after symptom onset have previously been suggested to be a reliable biomarker in ischemic stroke and to correlate with brain infarct volume, stroke severity, and long-term outcome." (PMID 32595585, 2020). "Captopril increased IL-8 from stroke-Mo and increased IL-6, IL-8, and MCP-1 secretions from MSCs." (PMID 32802081, 2020). "IL-6 is a key pro-inflammatory molecule and mediates stroke-induced inflammation." (PMID 32429999, 2020). "However, ADMA levels were associated with levels of IL-6 and CRP at several time points after stroke." (PMID 32150996, 2020). "An early pilot study demonstrated that IL-6 was an independent predictor of stroke risk in AF, but not CRP." (PMID 32154260, 2020). "IL-1β has been associated with stroke in SCA, and it has been suggested that IL-6 could be related to the development of pulmonary hypertension in SCA children." (PMID 33250889, 2020). "Furthermore, the level of amphiregulin (a VEGF ligand) secreted from Treg cells is elevated in the chronic stages of stroke; it regulates the IL-6 and STAT3 pathways and ameliorates neurological deficits." (PMID 32174916, 2020). "Our results showed that a higher temperature at 24 but not 6 h after stroke was associated with failed reperfusion (OR: 0.373, p = 0.001), poor outcome (OR: 2.190, p = 0.005) and higher IL-6 levels (OR: 0.958, p < 0.0001)." (PMID 32635529, 2020).
Stroke (continued). "Importantly, the systemic inhibition of miR-141c, which is upregulated in the brain of socially isolated mice after stroke, resulted in the transcriptional upregulation of IL-6." (PMID 33193727, 2020). "Primary studies showed that IL6 is the best proinflammatory biomarker in case of stroke." (PMID 33082828, 2020). "Polymorphisms in a number of candidate genes, such as IL-6, BDNF, COX2, CYPC19, and GPIIIa could be associated with stroke outcome and recovery." (PMID 33049931, 2020). "A study utilizing oral administration of PLX3397 to silence the CSF1R in rats prior to stroke reported that it exacerbated stroke severity and actually increased the infarct size at 3 days by increasing the production of inflammatory mediators by astrocytes (IL-1b, iNOS, IL-6)." (PMID 32345303, 2020). "Additionally, prospective studies showed that high IL-6 levels independently predicted stroke in patients with AF, and the addition of IL-6 resulted in improved prediction performance of the CHA2DS2-VASc clinical risk stratification schemes." (PMID 31616316, 2019). "Stroke-induced release of pro-inflammatory mediators and cytokines leads to brain cell damage and apoptosis, specifically tied to increased levels of pro-inflammatory cytokines IL-6 and TNF-α." (PMID 31354401, 2019). "Notably, there was a controversy regarding the source of elevated IL-6 levels in the early stroke phase; IL-6 possessed multipotent functions and was upregulated during brain injury or the repair process." (PMID 31164999, 2019). "By leveraging recent GWAS data we highlighted that targeting IL6 and its signaling pathway could decrease AF, stroke, CAD, and AAA." (PMID 31552141, 2019). "One previous study demonstrates that IL-6 promotes post-stroke angiogenesis and functional recovery, but the cellular source of IL-6 during stroke recovery is unknown." (PMID 31133816, 2019). "The main proinflammatory cytokines in stroke are TNFα, IL-1β, and IL-6." (PMID 31544811, 2019). "Here, we sought to determine whether IL-6 was involved in the promoting role of hyperforin in angiogenesis after stroke." (PMID 31133816, 2019). "Likewise, what are the mechanisms involved in stimulating the meningeal MCs to release IL-6 after a stroke?" (PMID 31001088, 2019). "Anti-IL-6 significantly decreased the number of BrdU+/DCX+ cells in the ischemic SVZ (99 ± 6 vs. 70 ± 7, P < 0.01) and striatum (68 ± 9 vs. 31 ± 5, P < 0.01) of hyperforin-treated mice at 28 dpi, indicating that hyperforin promotes post-stroke neurogenesis via IL-6." (PMID 31133816, 2019). "Similar to TNF-α and IL-1β, Il-6 levels are elevated in CSF of severe stroke patients." (PMID 31291966, 2019). "The knockdown of miR-181a enhanced the production of pro-inflammatory cytokines (TNF-α, IL-6, IL-1β, IL-8), and increased levels of the anti-inflammatory cytokine IL-10 result from miR-181 over-expression in a murine stroke model." (PMID 30953275, 2019). "The astrocytic IL-6 was essential to the promoting effects of hyperforin on the neural precursor cells proliferation, neuronal differentiation, angiogenesis, and functional recovery after stroke." (PMID 31133816, 2019). "However, in PT mice miR-124 NPs were able to specifically augment interleukin-6 levels at day 2 post-stroke." (PMID 29494665, 2018). "In the same study it was shown that the vasculature of the stroke mice changed to a non-capillary large vessel phenotype in the STAT3 endothelial knockout stroke mice, suggesting that IL6 production of nearby cells, for example pericytes, would contribute to tissue recovery after stroke." (PMID 29518129, 2018). "Interestingly, elevated TNF-α expression and further enhanced IL-6 levels were reported in stroke rats subjected to RIC pretreatment." (PMID 30115811, 2018). "Consistently, IL6-/- mice have increased stroke infarct volumes." (PMID 29518129, 2018).